AMACR (alpha-methylacyl-CoA racemase)
Diseases named in the same sentence as AMACR in open-access papers (continued):
Sharing a sentence is not in itself a finding about the gene and the disease.
colon carcinoma (6 papers, 2009 to 2024). "Alpha-methylacyl-coenzyme A racemase (AMACR) regulates peroxisomal β-oxidation of phytol-derived, branched-chain fatty acids from red meat and dairy products — suspected risk factors for colon carcinoma (CCa)." (PMID 19148275, 2009). "The AMACR protein band in LNCaP was found to be more intense that of the CaCo-2 cell line, a colon cancer cell line commonly used as a positive control for AMACR." (PMID 30613352, 2018). "In contrast they identified a high prevalence (89%) of deletion of CG12-16 in moderately differentiated colon cancers with strong AMACR overexpression, whereas these deletions existed in only 14% of poorly differentiated colon cancer." (PMID 24152881, 2013). "In contrast AMACR overexpression was found in villous adenoma and high and moderately differentiated colon cancer." (PMID 24152881, 2013). "Therefore, we speculate that AMACR and LY75 may inhibit tumor mutation burden in colon cancer and lead to decreased MSI levels, while the suppressed anti-tumor immune response will further reduce the risk of colon cancer recurrence and proliferation." (PMID 39726813, 2024). "A close examination of the AMACR gene in a panel of normal and progressively malignant colon tissues reveals that deletions of specific sequences in the AMACR gene may trigger its abnormal expression during the evolution of colon cancer." (PMID 19148275, 2009). "As anticipated, no AMACR was detected at either the protein or mRNA level in prostate epithelial cells (PrEC) isolated from healthy prostate tissue and in the colon cancer cell line HT-29." (PMID 30613352, 2018). "Here, we show that AMACR is also highly expressed in certain stages of colon cancer, though not all stages." (PMID 19148275, 2009).
colorectal cancer (6 papers, 2009 to 2024). A primary or metastatic malignant neoplasm that affects the colon or rectum. "In a recent study on 1315 colorectal cancers AMACR overexpression was found to be associated with left-side tumour localisation in colorectal cancer." (PMID 24152881, 2013). "AMACR overexpression has been observed in prostate and colorectal carcinomas, and linked to a high-fat diet." (PMID 22782380, 2012). "Another possible explanation would be a specific supportive role of AMACR in the development of precursor lesions in the colorectal cancer carcinogenesis." (PMID 24152881, 2013). "AMACR is essential for the completion of the β-oxidation pathway and has recently been shown to upregulated in colorectal cancer and adenoma; 4) BRAF, MLH1 and β-catenin as additional markers involved in the serrated adenocarcinoma carcinogenesis." (PMID 24152881, 2013). "Moreover, AMACR is positively expressed in 81.7% of patients with colorectal cancer and is significantly correlated with several clinical features but not with patient outcomes." (PMID 39726813, 2024). "Interestingly, six SBAs (two CD-SBAs and four Spo-SBAs) displayed a full colorectal carcinoma (CRC)-like immunoprofile (CK7−/CK20+/CDX2+/AMACR+/SATB2+); none of them was a CrD-SBA." (PMID 33228145, 2020).
hepatocellular carcinoma (6 papers, 2008 to 2024). A malignant tumor that arises from hepatocytes. "One patient had a hepatocellular carcinoma at the time of the AMACR deficiency diagnosis and two patients suffered from gallstones." (PMID 39313810, 2024). "Wei Li proved that high AMACR in the cytoplasm of hepatocellular carcinoma tumor cells was significantly associated with venous invasion, suggesting an important role of this enzyme in tumor invasiveness." (PMID 21627811, 2011). "Patients diagnosed with AMACR deficiency should follow up for malignancies, especially hepatic carcinoma that may develop due to the metabolic disorder of the liver." (PMID 39544692, 2024). "Recently a link between β-catenin gene mutation and overexpression of the enzyme α-methylacyl-CoA racemase (AMACR, also known as P504S) was found in hepatocellular carcinomas, suggesting that the latter is regulated by β-catenin-mediated signaling." (PMID 26888362, 2016). "One patient in our cohort had a hepatocellular carcinoma at the time the AMACR deficiency diagnosis was established and one (unreported) sibling of another patient who died of liver cancer was not evaluated for AMACR deficiency." (PMID 39313810, 2024). "This study aims to evaluate immunohistochemical expression of the AMACR in neoplastic and nonneoplastic liver lesions, and assess its value in the diagnosis of hepatocellular carcinoma (HCC)." (PMID 18577240, 2008).
liver cancer (6 papers, 2019 to 2024). An epithelial or non-epithelial malignant neoplasm that arises from the liver. "Another patient had a sibling who died of liver cancer, who was not evaluated for AMACR deficiency at the time." (PMID 39313810, 2024). "At the cellular level, YBX3 and CH25H were highly expressed in liver cancer cell lines, and ABCA6, PLIN5, AMACR, AKR1D1, CYP27A1, CYP46A1 were highly expressed in liver cancer cell lines in CCLE." (PMID 32627826, 2020).
adenoma (5 papers, 2009 to 2022). A neoplasm arising from the epithelium. "It is now necessary to identify in which processes AMACR and p16Ink in distal HPs are involved and if their dysregulation is implicated in the development of certain subgroups of adenomas." (PMID 24152881, 2013). "Intriguingly, several studies have demonstrated that AMACR is expressed preferentially in differentiated CRCs and its precursor lesions (adenomas)." (PMID 33755595, 2021). "We first provided a detailed description of the relationship between AMACR expression levels and the sequence of adenoma-carcinoma progression in the colon." (PMID 19148275, 2009). "We observed a strong positive correlation between AMACR expression and the sequence of adenoma-carcinoma progression, suggesting a promotional function of AMACR in colon carcinogenesis." (PMID 19148275, 2009). "This hypothesis is supported by recent data demonstrating increased AMACR expression in high grade dysplasia compared to low grade dysplasia in conventional adenomas." (PMID 24152881, 2013). "However, the relationship between levels of AMACR expression and the sequence of adenoma-carcinoma progression in the colon has not been fully characterized." (PMID 19148275, 2009).
benign prostatic hyperplasia (5 papers, 2005 to 2022). A non-cancerous nodular enlargement of the prostate gland. "Overexpression of AMACR - at both mRNA and protein levels - has been reported in cancerous prostatic tissue when compared to benign prostatic hyperplasia (BPH) and normal prostate tissue." (PMID 26928323, 2016). "Benign prostatic hyperplasia glands stained primarily with a moderate intensity for claudin-4 compared with PSMA and AMACR, which stained at low intensity and negatively, respectively." (PMID 18648369, 2008).
metastatic disease (5 papers, 2006 to 2025). "Our RNA-seq analysis confirmed the widespread cancer-specific expression of AMACR at the transcript level suggesting that our molecular-genetic imaging strategy can be employed to image both localized and metastatic disease." (PMID 30613352, 2018). "Analysis of the RNA-seq datasets further supports the cancer-specificity of AMACR and its ubiquitous expression in both primary and metastatic disease." (PMID 30613352, 2018). "Moreover, it is reported that AMACR expression is decreased in castration-resistant metastatic diseases." (PMID 20003233, 2009). "Furthermore, we have shown that AMACR expression is highest in localised prostate cancer and decreases in metastatic disease, and subsequent reductions in AMACR expression in the former is associated with an increased rate of biochemical recurrence." (PMID 16880794, 2006). "At the protein level, the expression of AMACR has been identified in both primary and metastatic disease with little to no expression in healthy tissues." (PMID 30613352, 2018).
Refsum disease (5 papers, 2015 to 2022). Refsum disease, biochemically characterised by phytanic acid accumulation, belongs to the group of leucodystrophic diseases. "Mutations directly associated with the peroxisomal fatty acid α-oxidation pathway are extremely rare, with an estimated 1 in 106 incidence of Refsum disease in the UK, while only a handful of AMACR deficient patients have been reported in the literature." (PMID 35055171, 2022). "We used a lipidomics approach to investigate the lipid composition of plasma samples from patients with peroxisomal disorders, including RCDP, ZSD, DBP and AMACR deficiency, and Refsum disease." (PMID 29209936, 2018). "Recently, phytanic and pristanic acid were shown to be converted into phytanoyl- and pristanoyl-carnitine in plasma samples from patients with Refsum disease and AMACR deficiency, respectively." (PMID 29209936, 2018). "Dependent on the most prominent presenting symptom such as retinitis pigmentosa, cerebellar ataxia or adrenal insufficiency, other single peroxisomal enzyme deficiencies like classical Refsum disease, alpha-methylacyl-CoA racemase deficiency or X-ALD should be considered." (PMID 26627182, 2015). "We found good correlations of both phytanic levels and pristanic acid levels with the levels of a variety of phospholipid species in plasma samples from Refsum disease, RCDP type 1 and 5, and AMACR deficiency, respectively." (PMID 29209936, 2018). "These characteristic phospholipid species could be novel diagnostic biomarkers when lipidomics is used as a screening tool for peroxisomal diseases such as ZSDs, Refsum disease, RCDP, and AMACR deficiency." (PMID 29209936, 2018).
renal tumors (5 papers, 2013 to 2025). "Though morphology alone is often sufficient for diagnosis after RTB, immunohistochemistry (IHC) is becoming increasingly useful when uncertainty exists, and an initial panel of CK7/AMACR/CAIX has been recommended for subtyping of the most common renal tumours." (PMID 40264828, 2025). "Characterization of the renal tumors by immunohistochemistry showed the expression of AMACR, a peroxisomal and mitochondrial enzyme involved in the β-oxidation of branched-chain fatty acids and fatty acid derivatives." (PMID 24148528, 2013). "A recent article highlighted the utility of a panel that includes CA IX, CD10, AMACR, CK7, and CD117 if the differential diagnosis is limited to common primary renal tumors—such as clear cell RCC, papillary RCC, and chromophobe RCC." (PMID 25889632, 2015). "AMACR (P504S), as a specific and sensitive marker of PRCC, is also highly expressed in OPRCC, while its expression is relatively small and weak in the immunohistochemistry of other renal tumors." (PMID 39957804, 2024).
urothelial carcinoma (4 papers, 2011 to 2023). A malignant neoplasm derived from the transitional epithelium of the urinary tract (urinary bladder, ureter, urethra, or renal pelvis). "The positivity for AMACR is also not helpful because this marker has been reported to be positive in urothelial carcinoma, which could exhibit squamous differentiation as well." (PMID 21627811, 2011).
adenosis (3 papers, 2008 to 2012). "AMACR expression is also identified in 4%-21% of benign prostatic glands in up to 18- 27% of cases of adenosis and in 18-58% of cases of nephrogenic adenoma." (PMID 21176184, 2010). "For example, AMACR may also be expressed in high grade PIN, in atypical adenomatous hyperplasia (adenosis) and even in atrophic or benign glands." (PMID 22800084, 2012). "Those with a negative AMACR and positive labeling with HMWCK in the basal cells as adenosis, atrophy and those with positive labeling with HMWCK in the luminal cells as basal cell hyperplasia." (PMID 21176184, 2010).
cholestasis (3 papers, 2013 to 2024). Impairment of the bile flow caused by obstruction within the liver, or outside the liver in the bile duct system. "Alpha-methylacyl-coA racemase deficiency has also been reported in four infants although clinical presentation differed to that seen in adults with abnormal bile acid synthesis, coagulopathy and neonatal cholestasis." (PMID 23286897, 2013). "Liver involvement in AMACR deficiency may include hepatomegaly, hepatosteatosis, and cholestasis." (PMID 39544692, 2024). "Since also none of the adults in our cohort had a history of cholestasis, we conclude that the previous reported neonatal cholestasis in AMACR deficiency is most likely a very rare manifestation of disease or may have had a different cause in this particular patient." (PMID 39313810, 2024).
endometrioid carcinoma (3 papers, 2021 to 2023). "The overall immunoreactivity of AMACR in both ovarian and endometrial clear cell carcinoma, endometrioid carcinoma, and serous carcinoma was generally 47.5%, 19.5%, and 0%, respectively." (PMID 37383161, 2023). "The immunoreactivity of AMACR in ovarian clear cell carcinoma, endometrioid carcinoma, and serous carcinoma in the ovary was 58%, 10%, and 0%, respectively." (PMID 37383161, 2023). "Also, the expression of HNF1β, Napsin A, and AMACR markers was reported in 101 cases of serous carcinoma 7%, 1%, and 1% and in endometrioid carcinoma 37%, 5.3%, and 0%." (PMID 37383161, 2023).
gastric cancer (3 papers, 2020 to 2024). A primary or metastatic malignant neoplasm involving the stomach. "In Lee’s study, AMACR expression was associated with tumor depth and TNM stage, with a higher positive rate in early gastric cancer than in advanced stages." (PMID 39336516, 2024). "Moreover, the clinicopathological significance and prognostic relevance of AMACR in gastric cancer have also been documented." (PMID 39336516, 2024). "Notably, AMACR expression is the lowest in Stage IV gastric cancers." (PMID 39336516, 2024).
metanephric adenoma (3 papers, 2023 to 2025). A benign, well-circumscribed renal cortical neoplasm affecting females more often than males. "The examined markers are CD56, CD57, WT1, AMACR, KRT7, and KRTAE1/AE3, which assist to separate nephroblastoma with epithelial predominance from morphologically indistinguishable metanephric adenoma." (PMID 40177273, 2025).
Pigmentary retinopathy (3 papers, 2013 to 2024). An abnormality of the retina characterized by pigment deposition. "Alpha-methylacyl-coA racemase deficiency presents heterogeneously in adults, with peripheral neuropathy, pigmentary retinopathy, seizures and relapsing encephalopathy being common features." (PMID 23286897, 2013). "Ocular features of AMACR deficiency include pigmentary retinopathy, cataract, and optic atrophy." (PMID 39544692, 2024).
serous carcinoma (3 papers, 2021 to 2023). "It means that AMACR is a lower specific marker for the distinction of endometrioid from CCC than serous carcinoma." (PMID 37383161, 2023).
bladder adenocarcinoma (2 papers, 2016 to 2018). "In urachal adenocarcinomas, AMACR was found to be positive in a low number of cases (17%), while in colorectal and primary bladder adenocarcinomas, a significantly higher number (>66%) of cases exhibited AMACR-reactivity." (PMID 29721106, 2018).
cerebellar ataxia (2 papers, 2015 to 2022). A neurological syndrome characterized by clumsy and uncoordinated movement of the limbs, trunk, and cranial muscles. "However, AMACR genomic variants are associated with relapsing encephalopathy and cerebellar ataxia." (PMID 35431771, 2022).
chondrosarcoma (2 papers, 2016 to 2024). A malignant cartilaginous matrix-producing mesenchymal neoplasm arising from the bone and soft tissue. "AMACR helps differentiate between benign enchondromas and malignant chondrosarcomas, while periostin is present in low-grade chondrosarcomas but not in enchondromas, aiding diagnosis." (PMID 39590345, 2024). "AMACR should be used for differential diagnosis of chordomas from chondrosarcomas in combination with the classical stains EMA and CKs." (PMID 26888362, 2016). "Our aim was to evaluate the IHC expression of α-methylacyl-CoA racemase (AMACR/P504S), β-catenin and E-cadherin in chordomas relative to chondrosarcomas and assess the utility of these markers for differential diagnosis." (PMID 26888362, 2016). "In conclusion, our study is the first to show that AMACR is expressed in most of the chordomas but only in a minority of chondrosarcomas." (PMID 26888362, 2016). "To test our hypothesis we have assessed by IHC stains the expression of E-cadherin, β-catenin and AMACR in a cohort of chordomas and compared it to a set of chondrosarcomas." (PMID 26888362, 2016). "We have shown that AMACR is differentially expressed in chordomas and chondrosarcoma." (PMID 26888362, 2016). "Moreover, we have found that AMACR may serve as IHC marker of chordoma, assisting in the differential diagnosis with chondrosarcoma." (PMID 26888362, 2016).
collecting duct carcinoma (2 papers, 2013 to 2022). "Previously, we found that immunoreactivity for AMACR is useful to distinguish papillary RCC from collecting duct carcinoma." (PMID 24083046, 2013).
colorectal adenoma (2 papers, 2024 to 2025). An adenoma that arises from the colon or rectum. "Additionally, an important enzyme for cholesterol metabolite oxidation is α‐Methylacyl‐CoA racemase (AMACR), which is notably overexpressed in colorectal adenomas and cancer." (PMID 40785042, 2025). "Additionally, the expression of AMACR in colorectal adenoma and carcinoma tissues is higher than that in non-tumoral epithelial tissues, suggesting its potential role in tumor formation." (PMID 39726813, 2024).
dysplasia (2 papers, 2020 to 2024). A usually neoplastic transformation of the cell, associated with altered architectural tissue patterns. "AMACR expression has also been identified in dysplasia associated with Barrett’s esophagus and inflammatory bowel diseases." (PMID 39336516, 2024). "Furthermore, AMACR expression has also been studied in dysplasia associated with Barrett’s esophagus." (PMID 39336516, 2024). "In the gastric dysplasia cases, AMACR expressions were evaluated and divided into low- and high-grade dysplasia." (PMID 39336516, 2024). "Upon further analysis, the luminal pattern of AMACR expression was found to be more prevalent in low-grade dysplasia than in high-grade dysplasia or gastric adenocarcinoma (p < 0.001)." (PMID 39336516, 2024). "Moreover, AMACR expression is significantly higher in the stomach in high-grade dysplasia than in low-grade dysplasia (76.0% vs. 4.5%)." (PMID 39336516, 2024). "However, the luminal pattern of AMACR expression was observed in 30.0% and 6.3% of high-grade dysplasia and adenocarcinoma cases, respectively." (PMID 39336516, 2024). "The negative rates of AMACR expression in overall lesions were 15.1 ± 23.9%, 49.0 ± 29.9%, and 59.0 ± 32.2% in low- and high-grade dysplasia and gastric adenocarcinoma groups, respectively." (PMID 39336516, 2024). "AMACR has also been found to be expressed in cases of IM with dysplasia, with an incidence of 20, 40 and 80% in cases of indefinite, low-grade and high-grade dysplasia, respectively, but it is negative in cases of IM without dysplasia." (PMID 31904088, 2020).